GRB14 (growth factor receptor bound protein 14)
Description:
Adapter protein which modulates coupling of cell surface receptor kinases with specific signaling pathways. Binds to, and suppresses signals from, the activated insulin receptor (INSR). Potent inhibitor of insulin-stimulated MAPK3 phosphorylation. Plays a critical role regulating PDPK1 membrane translocation in response to insulin stimulation and serves as an adapter protein to recruit PDPK1 to activated insulin receptor, thus promoting PKB/AKT1 phosphorylation and transduction of the insulin signal.
Tractability: Small molecule: a structure with a bound ligand is known. Antibody: UniProt places it where antibodies can reach, with high confidence; its Gene Ontology location is reachable by antibodies, with high confidence. PROTAC: its protein half-life has been measured.
Gene: Protein-coding gene on chromosome 2 (164,492,417 to 164,622,472, reverse strand). Ensembl gene ENSG00000115290.
Subcellular location: Cytoplasm; Endosome membrane
Subcellular location (Human Protein Atlas): Cytosol; Nucleoplasm
Pathways (Reactome):
Hemostasis: Tie2 Signaling
Gene Ontology:
Molecular function: molecular adaptor activity; protein binding; receptor tyrosine kinase binding; protein-macromolecule adaptor activity
Biological process: negative regulation of insulin receptor signaling pathway; insulin receptor signaling pathway; intracellular signal transduction; signal transduction
Cellular component: cytoplasm; endosome membrane; plasma membrane; cytosol
Genetic constraint (gnomAD): Loss-of-function variants: 21 observed, 32.18 expected, observed/expected ratio (o/e) 0.65, 90% interval 0.46 to 0.94. The upper end of that interval is the gene's LOEUF score, 0.94, which puts it in group 3 of 6, group 1 being the genes least tolerant of losing a copy. Missense variants: 395 observed, 365.54 expected, observed/expected ratio (o/e) 1.08, 90% interval 0.99 to 1.17. Synonymous variants: 144 observed, 137.29 expected, observed/expected ratio (o/e) 1.05, 90% interval 0.92 to 1.2.
Homologues: Orthologues: chimpanzee GRB14 (100% identical), macaque GRB14 (99% identical), pig GRB14 (98% identical), dog GRB14 (96% identical), rabbit GRB14 (95% identical), mouse Grb14 (86% identical), guinea pig GRB14 (85% identical), rat Grb14 (85% identical), zebrafish GRB14 (43% identical), tropical clawed frog grb14 (24% identical), Drosophila melanogaster pico (22% identical), Caenorhabditis elegans mig-10 (17% identical). Paralogues in human: GRB10 (54% identical), GRB7 (46% identical), RAPH1 (28% identical), APBB1IP (24% identical).
Diseases named in the same sentence as GRB14 in open-access papers:
GRB14 is named in the same sentence as 31 diseases in open-access papers, as found by Europe PMC text mining. Sharing a sentence is not in itself a finding about the gene and the disease. The quoted sentences say what the papers report.
Obesity (16 papers, 2010 to 2025). Accumulation of substantial excess body fat. "In addition, the expression of GRB14 in adipose tissues was decreased significantly in women with obesity after weight loss through either lifestyle intervention or bariatric surgery." (PMID 32099031, 2020). "Previous studies have also identified numerous genetic loci and gene variants such as FTO, MC4R, ADAMTS9 and GRB14/COBLL1, which have been found to be associated with overweight/obesity and diabetes." (PMID 38089629, 2023). "Mediation analyses were used to determine the causal relationship between SNPs, AT GRB14/COBLL1 mRNA expression, and obesity-related traits." (PMID 35955692, 2022). "Our study focused on a WHR-associated locus harboring two candidate genes, GRB14 and COBLL1, in the context of effects on obesity, fat distribution, and metabolic parameters." (PMID 35955692, 2022). "GRB14 is a prerequisite for the development of insulin-sensitizing molecules to pathological states as obesity and type 2 diabetes." (PMID 23754948, 2013). "While PTP1B and Grb-14 functions were mainly explored with regard to their causal role in T2DM and obesity, the prevalence of insulin resistance in conjunction with type 1 diabetes has recently gained attention." (PMID 20815942, 2010). "In humans, GRB14 gene expression in skeletal muscle decreased after gastric bypass surgery accompanied by improved insulin sensitivity but increased in individuals with obesity." (PMID 35955692, 2022). "We hypothesize that GRB14/COBLL1 may act as the causal genes for FD-related SNPs (rs10195252 and rs6738627), and that they may be regulated by SNP to effect obesity-related metabolic traits." (PMID 35955692, 2022). "In contrast to GRB14, the link between obesity related traits and COBLL1 is less clear." (PMID 35955692, 2022). "In addition, CRYAB overexpression up-regulated GPD1 (FC > 1.5, p < 0.05), and in a human obesity study, triglyceride synthesis was reduced and muscle mass was increased by growth factor receptor bound protein 14 (GRB14) and GPD1." (PMID 36613828, 2022). "Both vis and sc GRB14/COBLL1 gene expression correlate with T2D, but vis GRB14 expression is more of a risk factor for glucose metabolism because its mRNA expression is associated with HbA1c, FPG, and T2D independently of obesity." (PMID 35955692, 2022). "Collectively, the genetic and biological evidence indicate that GRB14 has a key role in adipose distribution, and understanding the biological role of GRB14 may yield insights into potential therapeutics used to treat the rapidly growing obesity epidemic." (PMID 28073971, 2017). "Using the same method, seven highly ranked genes (BAP1, GRB14, HSP90AB1, ITGA5, NCKAP5L, SP1, and TOMM5) within ±1 Mb of obesity SNPs were identified." (PMID 24455749, 2013). "Here, we report significantly higher expression of COBLL1 and GRB14 in vis AT in patients with T2D, which seems to be independent of obesity." (PMID 35955692, 2022). "For example, of the four loci discovered by the recently discussed GWAS in BF% (in or near COBLL1/GRB14, IGF2BP1, PLA2G6, CRTC1) and in the most recent GWAS of obesity as measured by BMI only a very small number of these overall obesity loci exhibited sexual dimorphism (approximately 3–5%)." (PMID 28073971, 2017). "It must be acknowledged that despite the clear evidence for strong correlations between COBLL1 and GRB14 mRNA expression levels in AT and metabolic traits related to obesity, the observed findings do not allow for drawing any conclusions regarding causal relationships between these entities." (PMID 35955692, 2022).
Insulin resistance (11 papers, 2008 to 2024). Increased resistance towards insulin, that is, diminished effectiveness of insulin in reducing blood glucose levels. "In this group, a mutation in the region of the Grb14 gene has been suggested to be what drives insulin resistance, given that Grb14 is an effector of insulin signaling and directly inhibits insulin receptor catalytic activity in vitro." (PMID 37217826, 2023). "Associations of T2D risk alleles with increased fasting insulin and HOMA-IR implicate GRB14 variants playing a role in insulin resistance." (PMID 26363598, 2015). "Insulin resistance increases the risk of developing type 2 diabetes (T2D), and the inhibition of GRB14 may improve glucose homeostasis in T2D." (PMID 38674024, 2024). "Although further studies are needed to better understand the role of Grb14 in the cardiovascular system and the translatability of the animal data for humans, our study suggests the feasibility of inhibiting Grb14 to treat insulin resistance." (PMID 32099031, 2020). "The C allele of rs13389219 near GRB14 (p = 0.026) and A allele of rs10423928 in the intron of the GIPR gene (p = 0.012) showed worse insulin resistance (increased HOMA2-IR)." (PMID 30089489, 2018). "Among the targets implicated in insulin resistance, the genetic characterization and protein function of Grb14 have been clarified without contradiction." (PMID 38202781, 2023). "GRB14 expression is under hormonal control since it is downregulated by estradiol and upregulated by insulin, and overexpression of GRB14 has been detected in animal models and human patients exhibiting insulin resistance due to type 2 diabetes." (PMID 19424485, 2008). "S1-promoted GRB14, which is a negative regulator of the insulin receptor (INSR), represses post-receptor insulin signaling and increases insulin resistance." (PMID 38674024, 2024). "Notably, Grb-14 (GRB14) and PTP1B (PTPN1) are known molecular constituents of insulin resistance and development of PTP1B inhibitors for therapeutic modulation of insulin sensitivity is an active field of research." (PMID 20815942, 2010).
type 2 diabetes (10 papers, 2008 to 2024). "The remaining SNPs were directionally consistent with South Asian estimates and three (AP3S2 rs2028299, GRB14 rs3923113 and HNF4α rs4812829) were nominally (p < 0.05) associated with type 2 diabetes in DIAGRAM." (PMID 25145545, 2014). "Genes such as KCNE2, DLL1, ACVR1C, RGS3, MLXIPL (MLX interacting protein like), PAG1, SLC2A10 and GRB14 play important role in type 2 diabetes mellitus progression." (PMID 33902539, 2021). "Moreover, Grb14 expression is increased in adipose tissue of insulin-resistant animal models and type 2 diabetic patients, and improvement of insulin sensitivity in ob/ob mice by treatment with an antidiabetic drug (thiazolidinedione) is associated with a reduction in Grb14 expression." (PMID 29203791, 2017). "The seven loci shed new light on regions containing genes with a reported role for type 2 diabetes (PPARG, ADAMTS9, VEGFA), lipids (GRB14, MAP3K1) and hormone metabolism (HSD17B4)." (PMID 23754948, 2013).
diabetes (5 papers, 2020 to 2023). "We analyzed the association between COBLL1 and GRB14 mRNA expression and metabolic phenotypes, including diabetes, lipid, and inflammatory parameters, as well as adipokines." (PMID 35955692, 2022). "Consistent with previous results, GRB14 mRNA expression was lower in sc AT compared to vis AT in BMI ≥ 40 kg/m2 group, even under different pre- and diabetes states (p < 0.001)." (PMID 35955692, 2022). "While additional studies are needed to further confirm the efficacy and to de-risk potential negative cardiac effects in preclinical models, our data support the therapeutic strategy of inhibiting Grb14 to treat diabetes and related conditions." (PMID 32099031, 2020).
endometriosis (4 papers, 2015 to 2025). The growth of functional endometrial tissue in anatomic sites outside the uterine body. "A genome-wide enrichment analysis between endometriosis and obesity-related trait identified the association of GRB14 in both these conditions." (PMID 31169291, 2019). "Endometriosis-associated genes GRB14 and IGF2 play a role in insulin receptor signaling." (PMID 31169291, 2019). "Indeed, intergenic 7p15.2 and WNT4 risk loci show opposite directions of effect for WHRadjBMI and endometriosis, whilst the directionality is consistent for the GRB14 SNP." (PMID 37159502, 2023). "In addition to 7p15.2, weidentify four more variants with statistically significant evidence of involvement inboth endometriosis and WHRadjBMI (in/near KIFAP3,CAB39L, WNT4, GRB14); two ofthese, KIFAP3 and CAB39L, are novel associationsfor both traits." (PMID 25296917, 2015). "Considering loci with genome-wide significance for each trait, two endometriosis loci have lower P values than expected by chance in the WHRadjBMI GWAS: intergenic 7p15.2 and WNT4, and two of the 16 WHRadjBMI loci had P < 0.01 in the endometriosis GWAS: intergenic 7p15.2 and GRB14." (PMID 37159502, 2023).
breast carcinoma (3 papers, 2022 to 2024). "Interestingly, GRB14 was identified as a good prognostic factor for breast cancer patients; the overexpression of GRB14 was shown to inhibit estrogen-induced cell cycle progression." (PMID 38561388, 2024).
gastric cancer (3 papers, 2022 to 2026). A primary or metastatic malignant neoplasm involving the stomach. "This study reveals a novel mechanism wherein tRF-3005a promotes gastric cancer development by regulating RALY-mediated alternative splicing of SPAG4 to activate the GRB14/PI3K/AKT pathway, suggesting it may serve as a prognostic biomarker and therapeutic target." (PMID 41872130, 2026). "MAGE-A3 was significantly highly expressed in gastric cancer cell lines MGC803 and SGC7901, while the difference in GRB14 expression was not significant." (PMID 36367777, 2022).
glioblastoma (3 papers, 2021 to 2023). The most malignant astrocytic tumor (WHO grade IV). "Low-dose radiation stimulates GBM cells to secrete circ-METRN-rich SEVs, and circ-METRN enhances glioblastoma progression and radioresistance by regulating the miR-4709-3p/GRB14/PDGFRα pathway." (PMID 35999601, 2022). "Inhibition of GRB14 attenuated the tumor-promoting function of ldrEXOs although circ-METRN was highly expressed in glioblastoma cell lines previously treated with ldrEXOs." (PMID 33867829, 2021). "Knockdown of GRB14 (γ) or PDGFRα (δ) attenuated proliferation, radioresistance, apoptosis radioresistance, invasion, and migration abilities of glioblastoma cell lines previously treated with ldrEXOs." (PMID 33867829, 2021). "We identified the role of low-dose radiation-induced exosomal circ-METRN and miR-4709-3p/GRB14/PDGFRα pathway, bringing a novel insight into the investigation of exosomal circRNAs and providing potential targets for anti-glioblastoma therapy." (PMID 33867829, 2021). "In this study, increasing the expression level of GRB14 can rescue the proliferation, migration, and invasion of glioblastoma cells, despite the different expression levels of miR-4709-3p in different groups." (PMID 33867829, 2021). "Knockdown of miR-4709-3p (ε) or up-regulation of GRB14 (ζ) rescued progression and radioresistance of glioblastoma cell lines." (PMID 33867829, 2021). "Up-regulation of PDGFRα (ε) rescued progression and radioresistance of glioblastoma cell lines previously treated with knockdown of GRB14." (PMID 33867829, 2021). "The ldrEXOs-derived circ-METRN enhanced the glioblastoma progression and radioresistance via miR-4709-3p/GRB14/PDGFRα pathway." (PMID 33867829, 2021). "The mechanism of low-dose radiation-induced exosomal circ-METRN via miR-4709-3p/GRB14/PDGFRα pathway in glioblastoma cells was elucidated by using the schematic cartoon." (PMID 33867829, 2021). "GRB14 and PDGFRα exhibited high expression levels in glioblastoma tissues and cell lines." (PMID 33867829, 2021). "Besides, GRB14 was determined as a direct target of miR-4709-3p, and miR-4709-3p plays a further role in glioblastoma cell inhibition by targeting GRB14." (PMID 33867829, 2021). "Taken together, low-dose radiation-induced exosomal circ-METRN may exert its positive regulatory functions in glioblastoma progression and radioresistance via miR-4709-3p/GRB14/PDGFRα pathway." (PMID 33867829, 2021).
colorectal cancer (2 papers, 2024). A primary or metastatic malignant neoplasm that affects the colon or rectum. "GRB14 was previously shown to be a poor prognostic predictor for colorectal cancer; the overexpression of this gene can enhance cell invasion and result in the metastases of thyroid cancer." (PMID 38561388, 2024).
diabetic type 1 (2 papers, 2010 to 2013). "Consistent with this hypothesis, we found decreased phosphorylation of Grb14 in diabetic type 1 Ins2Akita mouse retinas." (PMID 24350791, 2013).
essential hypertension (2 papers, 2012 to 2023). Hypertension that presents without an identifiable cause. "This protein likely has an inhibitory effect on receptor tyrosine kinase signaling and thus on the insulin receptor signaling pathway, through which GRB14 variants may exert their effect on the development of hypertension." (PMID 22479346, 2012).
glioma (2 papers, 2023). A benign or malignant brain and spinal cord tumor that arises from glial cells (astrocytes, oligodendrocytes, ependymal cells). "GRB14 plays glioma-promoting roles through PDGFRα, which promotes glioma progression and treatment resistance." (PMID 37955724, 2023). "SHC2 and GRB14 are both linked to metabolism-linked cellular growth, and belong to SHC and GRB families; other members have been annotated as glioma pathway members [KEGG pathways." (PMID 36834486, 2023). "Expressions of candidates such as AFP, DLL1, and GRB14 were non-significant compared to normal samples; however, they were highly significant across different gliomas." (PMID 36834486, 2023).
Hyperinsulinemia (2 papers, 2020 to 2021). An increased concentration of insulin in the blood. "HFD feeding induced hyperinsulinemia in mice and the treatment with Grb14-shRNA markedly decreased plasma insulin levels in mice under various nutritional states compared with the empty vector." (PMID 32099031, 2020). "Exogenous insulin and consequent hyperinsulinemia may activate some signaling molecules (such as PHLPP1 and Grb14) and influence hepatocyte apoptosis." (PMID 34118892, 2021).
Lipedema (2 papers, 2024 to 2025). Disorder of adipose tissue characterized by symmetric and bilateral enlargement of the lower extremities due to abnormal deposition of subcutaneous fat often in obese women. "Of note, two of these loci, namely, VEGFA and GRB14‐COBLL1, were significantly associated with lipedema in an independent case–control study that included clinically diagnosed lipedema cases." (PMID 40425048, 2025).
asthma (1 paper, 2020). "In a placebo-controlled asthma intervention study, GRB14 was among the down-regulated genes explaining the effects of prednisolone on airway smooth muscle remodeling." (PMID 32142526, 2020).
cardiac hypertrophy (1 paper, 2020). "A previous study shows that mice with germline deficiency of Grb14 exhibits cardiac hypertrophy and dysfunction as measured by heart weight and fractional shortening." (PMID 32099031, 2020). "A previous report has shown that germline deletion of Grb14 in mice results in cardiac hypertrophy and impaired systolic function, which could severely limit the therapeutic potential of targeting Grb14." (PMID 32099031, 2020). "Despite the potential benefits of inhibiting Grb14 in disease settings, one study has shown that the global Grb14 KO mice have cardiac hypertrophy accompanied by impaired cardiac function, raising the potential safety concern for developing therapies of inhibiting Grb14 activity." (PMID 32099031, 2020). "Using an AAV carrying an shRNA against Grb14, we show here that efficient knockdown of Grb14 in the liver, the adipose tissue and the heart significantly improved glucose homeostasis without inducing cardiac hypertrophy or dysfunction." (PMID 32099031, 2020).
cardiomyopathy (1 paper, 2025). A disease of the heart muscle or myocardium proper. "Interestingly, loss of Grb14 can induce cardiomyopathy with increased fibrosis." (PMID 39761962, 2025).
central obesity (1 paper, 2013). "Our current and previously reported findings suggest that the rs6717858 near GRB14 has a female-specific effect on insulin as well as on central obesity and lipids." (PMID 23754948, 2013).
fatty liver disease (1 paper, 2020). A reversible condition wherein large vacuoles of triglyceride fat accumulate in liver cells via the process of steatosis. "Therefore, it is intriguing to speculate that Grb14 inhibition might also be beneficial in the context of fatty liver disease." (PMID 32099031, 2020).
myocardial infarction (1 paper, 2013). Gross necrosis of the myocardium, as a result of interruption of the blood supply to the area, as in coronary thrombosis. "A high expression of Grb14 in myocardial tissue activates the PI3K-Akt pathway: ablation of Grb14 results in myocardial infarction and decreased PI3K/Akt activation." (PMID 24350791, 2013).
sarcoma (1 paper, 2015). A usually aggressive malignant neoplasm of the soft tissue or bone. "Perhaps this is not surprising, given that most of the tumors from the irradiated Nf1+/- mice are sarcomas derived from muscle tissue, where Grb10 has a more prominent role than Grb14." (PMID 26000738, 2015).
thyroid cancer (1 paper, 2016). "Similarly GRB14 increases thyroid cancer cell growth by promoting RET signaling and its expression is correlated with human thyroid cancer invasiveness." (PMID 26788993, 2016).